MAPRE2 (microtubule associated protein RP/EB family member 2)
Description:
Adapter protein that is involved in microtubule polymerization, and spindle function by stabilizing microtubules and anchoring them at centrosomes. Therefore, ensures mitotic progression and genome stability. Acts as a central regulator of microtubule reorganization in apico-basal epithelial differentiation (By similarity). Plays a role during oocyte meiosis by regulating microtubule dynamics (By similarity). Participates in neurite growth by interacting with plexin B3/PLXNB3 and microtubule reorganization during apico-basal epithelial differentiation. Also plays an essential role for cell migration and focal adhesion dynamics. Mechanistically, recruits HAX1 to microtubules in order to regulate focal adhesion dynamics.
Synonyms: EB2; RP1; EB1; CSCSC2
Tractability: PROTAC: UniProt records ubiquitination sites on it; ubiquitination databases record sites on it; its protein half-life has been measured.
Gene: Protein-coding gene on chromosome 18 (34,976,928 to 35,143,470, forward strand). Ensembl gene ENSG00000166974.
Subcellular location: Cytoplasm, cytoskeleton
Gene Ontology:
Molecular function: identical protein binding; microtubule binding; protein binding; microtubule plus-end binding; protein kinase binding
Biological process: positive regulation of ARF protein signal transduction; positive regulation of focal adhesion disassembly; positive regulation of keratinocyte migration; protein localization to microtubule; regulation of microtubule polymerization or depolymerization; spindle assembly
Cellular component: cytoplasm; focal adhesion; microtubule cytoskeleton; microtubule plus-end; spindle midzone; cytoskeleton
Genetic constraint (gnomAD): Loss-of-function variants: 13 observed, 41.82 expected, observed/expected ratio (o/e) 0.31, 90% interval 0.2 to 0.49. The upper end of that interval is the gene's LOEUF score, 0.49, which puts it in group 2 of 6, group 1 being the genes least tolerant of losing a copy. Missense variants: 155 observed, 389.13 expected, observed/expected ratio (o/e) 0.4, 90% interval 0.35 to 0.46. Synonymous variants: 128 observed, 148.84 expected, observed/expected ratio (o/e) 0.86, 90% interval 0.74 to 1.
Homologues: Orthologues: chimpanzee MAPRE2 (99% identical), macaque MAPRE2 (99% identical), rabbit MAPRE2 (98% identical), guinea pig MAPRE2 (97% identical), dog MAPRE2 (97% identical), mouse Mapre2 (97% identical), rat AABR07031491.2 (97% identical), tropical clawed frog mapre2 (90% identical), zebrafish mapre2 (79% identical), pig MAPRE2 (74% identical), Caenorhabditis elegans ebp-1 (35% identical), Caenorhabditis elegans ebp-2 (30% identical), and 1 more. Paralogues in human: MAPRE3 (50% identical), MAPRE1 (47% identical).
Diseases named in the same sentence as MAPRE2 in open-access papers:
MAPRE2 is named in the same sentence as 31 diseases in open-access papers, as found by Europe PMC text mining. Sharing a sentence is not in itself a finding about the gene and the disease. The quoted sentences say what the papers report.
hepatocellular carcinoma (2 papers, 2020 to 2026). A malignant tumor that arises from hepatocytes. "It has been reported that MAPRE2 is overexpressed in hepatocellular carcinoma and esophageal squamous cell carcinoma; thus, MAPRE2 might be involved in tumorigenesis and promotion of tumor cell growth through Wnt signaling pathway or Aurora-B activation." (PMID 32426268, 2020).
pancreatic cancer (2 papers, 2020 to 2022). "MAPRE2 is highly expressed in pancreatic cancer cells and is associated with increased perineural invasiveness, poor outcome, and prognosis." (PMID 36009534, 2022).
bladder urothelial carcinoma (1 paper, 2020). "For example, in LUAD, renal papillary carcinoma, bladder urothelial carcinoma, and other cancers, MAPRE2 expression is significantly lower than that in normal tissues." (PMID 32426268, 2020).
Brugada syndrome (1 paper, 2024). A genetically heterogeneous condition characterized by complete or incomplete right bundle branch block accompanied by ST elevation in leads V1-V3. "CRATC1 was detected to have heart enhanced interaction with MAPRE2, which is associated with cardiac arrhythmia disorder, Brugada syndrome." (PMID 38848015, 2024).
cleft palate (1 paper, 2021). Cleft palate is a fissure type embryopathy that affects the soft and hard palate to varying degrees. "Our data provide evidence that MAPRE2 is involved in cellular migration of cranial neural crest and offers critical insights into the mechanism underlying the craniofacial dysmorphisms and cleft palate present in CSC-KT patients." (PMID 33654163, 2021). "Given that CSC-KT patients display cleft palate associated with highly specific facial dysmorphism, we hypothesize that MAPRE2 plays a crucial role in cranial neural crest migration during facial development." (PMID 33654163, 2021).
Intellectual disability (1 paper, 2020). "In terms of the intellectual development, patients with heterozygous variants in MAPRE2 had moderate to normal intelligence, while homozygous patients presented more severe intellectual disability." (PMID 31903734, 2020).
intellectual impairment (1 paper, 2022). "Previous studies have shown that two patients with homozygous pathogenic variants in MAPRE2 had severe neurological dysfunction, accompanied by intellectual impairment and seizures, whereas there was no neurological dysfunction in the patients with pathogenic TUBB variants." (PMID 35747986, 2022).
presbycusis (1 paper, 2022). Bilateral hearing loss caused by progressive degeneration of cochlear structures and central auditory pathways, typically associated with the aging process. "In the GSE49543 data set, four genes (Ywhag, Mapre2, Fgf1, Acss2) were used to construct the prognostic model, and those four genes were significantly up-regulated in the rat model of presbycusis." (PMID 35463035, 2022).
cancer (6 papers, 2016 to 2024). A tumor composed of atypical neoplastic, often pleomorphic cells that invade other tissues. "Literature reveals that MAPRE2 is associated with the occurrence and development of malignant tumors." (PMID 32426268, 2020). "CCNB1 (Cyclin B) and Mapre2 (Microtubule-associated protein RP/EB family member 2) are involved in regulating cell cycle progression and spindle assembly during mitosis, serving as promising biomarkers in several cancers, including prostate." (PMID 39040241, 2024). "The genes GCK, MAPRE3, and MAPRE2 hold promise for guiding therapeutic strategies for organ-specific cancers." (PMID 38971308, 2024). "Therefore, MAPRE2 overexpression in various malignant tumors is positively correlated with tumor growth, nerve infiltration, and poor prognosis." (PMID 32426268, 2020). "However, using the public database ULACN, it was observed that the levels of MAPRE2 expression in different types of malignant tumors and normal tissues differ from those suggested in the literature." (PMID 32426268, 2020). "Therefore, MAPRE2 expression may be tissue-specific and plays a differential role in various malignant tumors." (PMID 32426268, 2020).
tumor (5 papers, 2010 to 2020). "Whether the patients with MAPRE2 pathogenic mutations have an increased risk of tumor formation is not well understood yet." (PMID 31903734, 2020). "A WB confirmed that WDHD1 expression was upregulated in A549/DDP tumor tissues, and MAPRE2 was upregulated in WDHD1 knockout tumor tissues." (PMID 32426268, 2020). "Following cisplatin exposure, the WDHD1 and MAPRE2 knockout groups facilitated cell proliferation and migration, inhibited apoptosis in A549/DDP cells, decreased apoptosis, and increased tumor size and growth rate in animal experiments." (PMID 32426268, 2020).
MAPRE2 also shares sentences with these, for which no sentence is quoted: infection (2 papers); atrial fibrillation (1); AUTS2 syndrome (1); Bovine mastitis (1); Cardiac-urogenital syndrome (1); colon cancer (1); coronary artery disease (1); encephalitis (1); esophageal cancer (1); esophageal squamous cell carcinoma (1); Granuloma (1); Joubert syndrome (1); lung adenocarcinoma (1); lung carcinoma (1); lymphoma (1); mastitis (1); neuroblastoma (1); ovarian carcinoma (1); Treacher-Collins syndrome (1); vasculitis (1); viral infections (1).